RAP2C (RAP2C, member of RAS oncogene family)
Description:
Small GTP-binding protein which cycles between a GDP-bound inactive and a GTP-bound active form. May play a role in cytoskeletal rearrangements and regulate cell spreading through activation of the effector TNIK. May play a role in SRE-mediated gene transcription.
Synonyms: DKFZp313B211
Tractability: Antibody: its Gene Ontology location is reachable by antibodies, with high confidence. PROTAC: ubiquitination databases record sites on it; its protein half-life has been measured.
Target class: Enzyme; Hydrolase
Gene: Protein-coding gene on chromosome X (132,203,024 to 132,219,495, reverse strand). Ensembl gene ENSG00000123728.
Subcellular location: Cytoplasm; Recycling endosome membrane
Pathways (Reactome):
Immune System: Neutrophil degranulation
Gene Ontology:
Molecular function: GDP binding; GTP binding; protein binding; transcription coactivator activity; GTPase activity; G protein activity
Biological process: establishment of endothelial intestinal barrier; negative regulation of cell migration; Rap protein signal transduction; regulation of protein tyrosine kinase activity; positive regulation of DNA-templated transcription; signal transduction
Cellular component: bicellular tight junction; cell-cell contact zone; cytoplasm; extracellular exosome; plasma membrane; recycling endosome membrane; tertiary granule membrane; bounding membrane of organelle; cytoplasmic vesicle membrane; cytosol; endomembrane system; membrane; recycling endosome
Homologues: Orthologues: chimpanzee RAP2C (100% identical), dog RAP2C (100% identical), guinea pig RAP2C (100% identical), macaque RAP2C (100% identical), mouse Rap2c (100% identical), rabbit RAP2C (100% identical), rat Rap2c (100% identical), pig RAP2C (99% identical), tropical clawed frog rap2c (97% identical), zebrafish rap2c (93% identical), Drosophila melanogaster Rap2l (67% identical). Paralogues in human: RAP2A (90% identical), RAP2B (84% identical), RAP1A (61% identical), RAP1B (60% identical), RIT1 (46% identical), RRAS2 (45% identical), HRAS (44% identical), NRAS (44% identical), RRAS (44% identical), KRAS (44% identical), DIRAS2 (43% identical), MRAS (43% identical), and 23 more.
Diseases named in the same sentence as RAP2C in open-access papers:
RAP2C is named in the same sentence as 17 diseases in open-access papers, as found by Europe PMC text mining. Sharing a sentence is not in itself a finding about the gene and the disease. The quoted sentences say what the papers report.
breast carcinoma (4 papers, 2017 to 2023). "This miRNA also promotes apoptosis and inhibits proliferation in breast cancer cells via the MAPK signaling pathway by targeting Rap2c." (PMID 37402449, 2023). "RAP2C has been found to be an important molecular switch in the mitogen-activated protein kinase (MAPK) signaling pathway in breast cancer; RAP2C reduces apoptosis and promotes proliferation and migration through the MAPK signaling pathway." (PMID 33664765, 2020). "Indeed, there were 5 genes that were present in our list and in the up regulated list for breast cancer (RAP2C, SPN, GINS2, ESPL1 and IRF7)." (PMID 29108258, 2017).
colorectal cancer (3 papers, 2021 to 2022). A primary or metastatic malignant neoplasm that affects the colon or rectum. "However, some reports have shown that Rap2c can suppress the EMT process of colorectal cancer and inhibit cancer cell migration and metastasis in a nuclear factor κB- (NF-κB-) dependent pathway." (PMID 33628783, 2021). "RAP2C has also been reported to be involved in TNF-α-induced colorectal cancer metastasis." (PMID 34122424, 2021). "In colorectal cancer, the RAP2 isoform RAP2C has been reported to weaken the migration and invasion of colorectal cancer cells via suppressing the epithelial mesenchymal transition (EMT)." (PMID 35538031, 2022).
osteosarcoma (3 papers, 2021 to 2025). A usually aggressive malignant bone-forming mesenchymal neoplasm, predominantly affecting adolescents and young adults. "Similarly to RAP2C, the role of WEE1 in Osteosarcoma has been researched and mentioned as a therapeutic target." (PMID 39869252, 2025). "Regarding RAP2C, previous research has highlighted the potential of this target gene as a therapeutic target in Osteosarcoma, a type of bone cancer occurring mostly in children and adolescents, however the exact role RAP2C plays in bone-related pathways is not discussed." (PMID 39869252, 2025).
disc degeneration (1 paper, 2021). "qRT-PCR results showed that the expression levels of ID1, RAP2C, and PTPRK were all significantly higher in NP tissues of the grade IV disc degeneration and high immunity groups." (PMID 34122424, 2021).
glioma (1 paper, 2021). A benign or malignant brain and spinal cord tumor that arises from glial cells (astrocytes, oligodendrocytes, ependymal cells). "Rap2C was identified as one of the proteins downregulated in glioma cells treated with BM-MSC-conditioned media, suggesting it might negatively regulate glioma cell invasion." (PMID 34576182, 2021).
melanoma (1 paper, 2023). A malignant, usually aggressive tumor composed of atypical, neoplastic melanocytes. "In melanoma, lncRNA LENOX interacts with RAP2C to regulate metabolism and promote resistance to MAPK inhibition." (PMID 37596700, 2023).
prediabetes (1 paper, 2020). "In conclusion, our present results show that mild prediabetes induces miRNA expression changes leading to altered gene expression of Jazf1, Zkscan1, and Rap2c, which may contribute to the diastolic dysfunction and may serve as potential drug targets." (PMID 32244869, 2020).
tumor (5 papers, 2017 to 2025). "In CPTAC data also, RAP2A exhibited most robust upregulation of mRNA and protein levels in tumor tissues compared to normal tissues, while expression of RAP2C was found to be reduced in tumor tissues compared to normal tissues." (PMID 34235179, 2021). "As expected, the suppressive effects of RAP2C were detected on tumor progression." (PMID 29238068, 2017).
cancer (2 papers, 2019 to 2021). A tumor composed of atypical neoplastic, often pleomorphic cells that invade other tissues. "The overexpression of target gene RAP2C can promote cancer cell migration and invasiveness ability, but it has lower expression in normal thyroid cells compared with early-stage PTC cells." (PMID 31126066, 2019). "RAP2C is overexpressed by TF NFE2L1 inducing cancer cell migration and invasiveness ability, it also has a higher basal level in early-stage PTC cells compared with normal thyroid cells, causing DNA methylation promoting gene activity and cell migration." (PMID 31126066, 2019).
RAP2C also shares sentences with these, for which no sentence is quoted: acute coronary syndrome (1 paper); Anxiety (1); bone cancer (1); coronary artery disease (1); endometriosis (1); hepatocellular carcinoma (1); lymph node metastasis (1); thyroid cancer (1).